CYLD (CYLD lysine 63 deubiquitinase)
Diseases named in the same sentence as CYLD in open-access papers (continued):
Sharing a sentence is not in itself a finding about the gene and the disease.
cancer (continued). "Some cancer cells escape from necroptosis by decreasing the expression of key necroptosis mediators, including CYLD, RIPK3, and MLKL." (PMID 35864548, 2022). "Later, genome sequencing approaches have revealed somatic CYLD alterations in other numerous human cancers, including non-small cell lung cancer, melanoma, glioblastoma, breast, ovarian, bladder, colon, and head and neck cancer." (PMID 34201751, 2021). "RAD18 is the E3 ligase that monoubiquitinates PCNA, a central signaling event in TLS and CYLD is a deubiquitinase involved in cancer and required for efficient TLS, as we have previously reported." (PMID 34203408, 2021). "Taken together, our results suggest that wild type CYLD is able to repress skin squamous cell tumor development and progression in vivo, in immunocompetent transgenic mice, offering a powerful anti-cancer target against this type of skin neoplasia." (PMID 34201751, 2021). "For these reasons, both USP30 and CYLD are currently targets for therapeutic development to treat Parkinson’s disease and cancer." (PMID 34391779, 2021). "In quite a number of cancers, downregulation of CYLD results in impaired cell proliferation and survival, which indicatives an antitumor potential of CYLD." (PMID 33952719, 2021). "In TNFR1 signaling, IKK-mediated phosphorylation at serine 418 of CYLD protects cancer cells against cell death by downregulating CYLD activity." (PMID 33919439, 2021). "As a result, in agreement with all these evidences indicating the pro-tumoral role of NF-kB in cancer, we found that the rare squamous cell skin tumors developed from keratinocytes expressing slightly higher levels of wild type CYLD present a better prognosis." (PMID 34201751, 2021). "miR-922 targets and inhibits CYLD expression, leading to promotion of c-Myc and cyclin D1 as well as cancer cell proliferation, thus presenting another possible mechanism for HCC promotion." (PMID 33952719, 2021). "Later studies found that STAT3 activates miR-21 and miR-181b-1 through PTEN and CYLD as part of an epigenetic switch that links inflammation to cancer." (PMID 34956174, 2021). "Genetic disruption of CYLD function can lead to embryonic lethality, increased cancer formation or developmental defects, suggesting a complex role of CYLD in regulating multiple signaling pathways." (PMID 33432113, 2021). "But there are special cases, CYLD can inhibit oral squamous cell in the metastasis of carcinoma, CYLD controls the downstream TGF-β pathway by regulating Smad7, thereby inhibiting the occurrence and development of cancer." (PMID 33498168, 2021). "Nuclear factor (NF)-κB signaling has well-established roles in cancer promotion and CYLD has been reported to negatively regulate this pathway through its deubiquitinating activity." (PMID 32549302, 2020). "This positive relationship between SMG7 and CYLD was found to be widely conserved in human cancer cell lines and renal carcinoma samples from The Cancer Genome Atlas." (PMID 32602581, 2020). "Our study now shows more cancer cells with hyperactivity in NF-kB signaling after CYLD knockout (11% in the control group, 18% in the knockout group, p-Value < 2.2×10−6) in the single-cell RNA sequencing analysis of the two groups of mouse xenografts." (PMID 32708712, 2020). "There are reports that DUBs such as USP7, CYLD, and A20 play dual roles in cancer, acting as both anti- and pro-tumorigenic enzymes according to the affected targets." (PMID 32549302, 2020). "On the contrary, STAT3 can activate miR-21 and miR-181b-1 via PTEN and CYLD, which is the switch linking inflammation to cancer in MCF10A cells." (PMID 31803051, 2019). "Further investigation by accumulating the clinical evidence will be definitely required to verify the relationship between CYLD expression and therapeutic effects of anti-cancer drugs." (PMID 31635163, 2019).
cancer (continued). "In this manuscript we report that the tumor suppressor CYLD, similarly to other renowned tumor suppressor genes, protects from premature aging and cancer." (PMID 30631004, 2019). "Various reports have indicated that CYLD plays an antitumor role in numerous malignant tumors by regulating various signaling pathways, including Wnt/β-catenin, nuclear factor-κB, and transforming growth factor-β." (PMID 29808164, 2018). "Given the importance of CYLD in inflammation and cancer, a better understanding of molecular mechanisms regulating CYLD activity is of considerable interest." (PMID 29755980, 2018). "Whilst for the NF-κB pathway, CYLD and TRAF3 mutations appear to occur at a similar high rate in both cancers (8–11% rates), followed by the same rate of mutations of NLRC5 (6% rates)." (PMID 29933636, 2018). "Insights from these investigations will be instrumental in developing CYLD as a potential target for cancer therapy." (PMID 30388174, 2018). "CYLD is mechanistically linked to vascular endothelial barrier function and anti-VEGF therapy in cancer." (PMID 29081889, 2017). "Currently, inhibitors of CYLD and other DUBs are under clinical development, since DUBs are attractive candidate molecules in different diseases, including cancer." (PMID 28203236, 2017). "DUBs are genetically altered in many human cancers (i.e., CYLD, A20, or USP6) or contribute to the stability of oncogenes or tumour suppressors (i.e., USP7, USP8, or BRCC3)." (PMID 27597804, 2016). "How TRAIP and CYLD functionally interact in cell cycle regulation and cancer development remains to be explored." (PMID 26369285, 2015). "CYLD, an ubiquitin hydrolase, has an expanding repertoire of regulatory roles in cell signalling and is dysregulated in a number of cancers." (PMID 25565632, 2014). "CYLD is usually downregulated in hypoxic environments, as observed in many cancer cell lines." (PMID 41562858, 2026). "The effects of A20 and CYLD on regulation of cancer cell function are distinct." (PMID 40896706, 2025). "This suggests that CYLD could be considered a potential predictive biomarker and target for therapeutic resistance in various cancers." (PMID 38287022, 2024). "CYLD has been classified as a tumour suppressor gene and has a crucial role in cancer pathogenesis." (PMID 39430072, 2024). "Whether these modifications which include phosphorylation and ubiquitination could be harnessed directly or through targeting of BCL3 upstream modifiers, as suggested for the cancer related deubiquitination enzyme CYLD, remains to be determined." (PMID 38195591, 2024). "CYLD lysine 63 deubiquitinase (CYLD) is a ubiquitin hydrolase enzyme that removes ubiquitin molecules from other proteins, and is critical in regulating various signalling pathways that are involved in inflammation, immunity, cell survival and cancer." (PMID 37387450, 2023). "Moreover, prolonged hypoxia in human papillomavirus (HPV)-positive cancer cells mediates the stimulation of the HPV-encoded E6 protein, which induces polyubiquitination and proteasomal degradation of CYLD." (PMID 37387450, 2023). "Our findings not only establish for the first time CYLD’s significance as a regulatory component of early reprogramming but also highlight its role as an extracellular matrix regulator, which has profound implications in cancer research." (PMID 37894364, 2023). "Cylindromatosis (CYLD), a deubiquitination enzyme, negatively regulates cancer progression." (PMID 35978827, 2022). "Although loss of CYLD expression is significantly associated with poor prognosis in a large variety of tumors, no clinically-effective treatment for CYLD-negative cancer patients is available." (PMID 36376983, 2022).
cancer (continued). "Cyld encoded a deubiquitinase cylindromatosis (CYLD), which could inhibit K63 ubiquitination and prevent activation of ERK1 in human cancer cells." (PMID 35274380, 2022). "Despite altered CYLD expression having been observed in various cancers in which EGFR signalling contributed to cancer development and progression, the roles of CYLD in EGFR signalling and response to anti-EGFR therapies remain unknown." (PMID 35008337, 2021). "Several other miRNAs were also reported to regulate CYLD in multiple cancer types." (PMID 34326699, 2021). "While NF-κB has been a target of cancer therapeutics, perhaps CYLD, as an upstream regulator, could also be target for therapeutic development for cancers and inflammatory diseases." (PMID 34391779, 2021). "In addition to the PTM of CYLD, miR-454 has been reported to negatively regulate CYLD, promoting cancer cell survival and resistance against oxaliplatin." (PMID 33919439, 2021). "Our results suggest that a moderate increase in CYLD levels could be useful for anti-cancer therapy." (PMID 34201751, 2021). "Pathologic and genetic characterization of these CYLD-mutant carcinomas, however, remains limited." (PMID 32892208, 2021). "In addition to its usefulness as prognosis biomarkers in various cancers, it has been reported that CYLD is also expressed in the middle ear and plays important roles in regulating inflammatory response." (PMID 33031450, 2020). "Therefore, CYLD plays a vital role in regulating NPC via mediating three cancer hallmarks, including proliferation, angiogenesis, and metastasis." (PMID 32708712, 2020). "Moreover, the cancer cells adjacent to fibroblasts and vasculature show high α-Sma staining in the CYLD knockout xenograft." (PMID 32708712, 2020). "The study of our transgenic mice has allowed us to know that the DUB function of CYLD is essential for the maintenance of the homeostasis of the skin and other organs, including thymus, lung, stomach, etc. preventing the development of cancer." (PMID 30631004, 2019). "CYLD has been reported as an important antitumor gene in numerous malignant tumors." (PMID 29808164, 2018). "CYLD is an important deubiquitinase and microtubule-binding protein that involves multiple cellular activities, including cell cycle progression, innate immune responses, and cancer." (PMID 28881612, 2017). "DUBs are critical key players in diverse processes such as (i) spermatogenesis (e.g. USP2, USP8, USP9y, USP14, USP26, Uchl-1, Uchl-3 and CYLD), (ii) cancer biology (e.g. USP7, USP10 and USP11), and (iii) stemness and differentiation (e.g. USP7, USP9x, USP22, USP44 and Psmd14)." (PMID 28659380, 2017). "Thus, it is important to determine if CYLD aberrations do confer any tissue-specific oncogenic activity in various human cancer types." (PMID 31093340, 2016). "Several mechanisms have been proposed to mediate CYLD downregulation in cancers." (PMID 24495516, 2014). "CYLD is a DUB enzyme which is lost in different types of human cancer." (PMID 21573132, 2011). "Moreover BCL3 has been implicated in TNF-alpha mediated signaling via stabilisation of RIP1 through CYLD ubiquitination in non-cancer cells suggesting that it may also have a role in TNF-alpha responses in the local microenvironment." (PMID 38195591, 2024). "While further research is needed to identify the effect of CYLD DUB deficiency in these metabolic processes, one valid hypothesis is that these changes correlate with the promotion of EMT, as it has been demonstrated in cancer development." (PMID 37894364, 2023). "The reconstitution of CYLD-p18 axis could be a promising approach for EBV-positive cancer therapy." (PMID 33654169, 2021). "CYLD inhibitory roles in the NF-kB pathway may serve as a link between cancer cells and TME." (PMID 32708712, 2020). "In addition, dysregulation of CYLD has been demonstrated in various other cancer entities." (PMID 25329885, 2014). "However, the exact role of CYLD in cancer development is not fully understood." (PMID 25329885, 2014).
cancer (continued). "We have identified the function of the CYLD-HDAC axis in radiotherapy and HDACi can increase the sensitivity of cancer cells and tumors to radiation therapy both in vitro and in vivo." (PMID 38287022, 2024). "Functional protein association network analysis of the gene frequently mutated in the recurrent tumors showed enrichment of genes that regulate the cancer cell cycle, that is, MRE11A, CDKN2A, and CYLD." (PMID 38477073, 2024). "Therefore, CYLD may be considered a new target for cancer therapy." (PMID 37176077, 2023). "CYLD and SMPD2 were characteristics of G2 cancer, and TNFR1, TNFR2, NFKB1, TAB2, and USP4 for G3 cancer." (PMID 37233761, 2023). "However, as an important TSG, the upstream regulatory mechanism of CYLD in cancer remains unclear." (PMID 34326699, 2021). "Strikingly, CYLD and SMG7 expression showed a near‐universal correlation in diverse human cancer cell lines and clear cell renal cell carcinoma patient survival." (PMID 32602581, 2020). "Unlike A20, inactivation of CYLD is related to the pathogenesis of T-lymphoblastic leukemia and cancers." (PMID 40731796, 2025). "Thus, we identified the function of the CYLD-HDAC axis in radiotherapy and blocking HDACs by Chidamide can increase the sensitivity of cancer cells and tumors to radiation therapy both in vitro and in vivo." (PMID 38287022, 2024). "In turn, a decrease in expression was noted for CYLD and CLIP3 in all cancer grades." (PMID 37233761, 2023). "Consistent with this hypothesis, in ARIH1 miniTurboID experiments we detect several interacting proteins with a role in EMT modulation and cancer progression, including TJP1 (ZO1), CYLD, and UPF1." (PMID 35102251, 2022). "The absence of CYLD DUB activity enhances cancer-promoting function and increases survival of cells." (PMID 36202787, 2022). "Six overexpressed oncogenes including BCL2, NOTCH1, SOX4, and CTNNB1 and 10 downregulated tumor suppressor genes including PRKCB, IRF1, CYLD, and TGFB1 were identified as the targets of the DE miRNAs, which may promote cancer development." (PMID 34336826, 2021). "In addition, recurrent breakpoints of SVs targeting cancer genes commonly occurred in frequently deleted regions, e.g., CDKN2A on 9p21.3, MAML2 and ATM on 11q21-22, RAD51B, and TRAF3 on 14q 24-32.3, CYLD and NLRC5 on 16q12.1-13." (PMID 34234122, 2021). "We speculate that CYLD could function to deubiquitinate specific substrates in signaling pathways such as NF-κB and JNK, which are well-known to be involved in promoting cancers." (PMID 33952719, 2021). "CYLD-mutant carcinomas with cylindroma-like histomorphology (n = 55) showed significantly lower TMB compared with CYLD-mutant cases showing basaloid histology without the distinctive hyaline globules (n = 14) (median 1.7 vs. 4.4 mut/Mb, p = 0.0058)." (PMID 32461623, 2020). "Additionally, we observed that the expression of cell death regulators such as CYLD, EZR, VAMP1, ANAX1, and FPR1 was increased in mild hyperthermia treated cancer cells, which was similar to LIUS treated cancer cells." (PMID 31355136, 2019). "This may suggest that CYLD, TRAF3 and NLRC5 aberrations are critical for oncogenesis for a major subset of these cancers." (PMID 29933636, 2018). "Specifically, CYLD removed lysine 63 and linear ubiquitin chains from RIP1 and promoted necroptosis in TNF receptor signaling, which was involved in the regulation of different cellular processes including inflammation, fibrosis, and cancer." (PMID 27738385, 2016). "MiR-181b and miR-21 target cylindromatosis (CYLD) and phosphatase and tensin homolog (PTEN), respectively, and down-regulation of CYLD and PTEN leads to NF-κB activation, therefore also acting as a part of the epigenetic switch linking inflammation to cancer." (PMID 26123544, 2015).
cancer (continued). "Moreover, CYLD is also able to inhibit HDAC6, a member of the HDAC family whose major substrate is α-tubulin, has become a target for drug development to treat cancer due to its major contribution in oncogenic cell transformation." (PMID 22911729, 2012). "CYLD is a deubiquitinating enzyme (DUB) which is absent or strongly down regulated in different types of human cancer." (PMID 21573132, 2011). "Those multiple anticancer drugs not effective for CYLD-negative cancer cells, are categorized as the cytotoxic chemotherapeutic agents, suggesting that loss of CYLD expression may also affect cell cycle progression or apoptosis." (PMID 36376983, 2022). "Both livers from canines, a preponderant animal for cancer research, and genetic-modified human HCC cells treated with hepatocarcinogen aristolochic acid I (AAI) were further used to reveal the possible relevance between 5-LO pathway activation and CYLD suppression." (PMID 35978827, 2022). "Also, CYLD knocking-out macrophages could increase JNK activity through ubiquitinizing TRAF-2 protein, and studies have confirmed that CYLD knocking-out mice were prone to cancers." (PMID 38246916, 2024). "Moreover, mice lacking functional CYLD have increased rates of cancer progression." (PMID 33952719, 2021). "However, the protein expression levels of CYLD were not consistent in different cancer species." (PMID 33827598, 2021). "Reduced CYLD expression is frequently found, predominantly in invasive lesions in primary HNSCC, which may at least partly explain why CTX is not as effective in this cancer as one would expect from preclinical data." (PMID 35008337, 2021).